CTNNB1 (catenin beta 1)
Description:
Key downstream component of the canonical Wnt signaling pathway. In the absence of Wnt, forms a complex with AXIN1, AXIN2, APC, CSNK1A1 and GSK3B that promotes phosphorylation on N-terminal Ser and Thr residues and ubiquitination of CTNNB1 via BTRC and its subsequent degradation by the proteasome. In the presence of Wnt ligand, CTNNB1 is not ubiquitinated and accumulates in the nucleus, where it acts as a coactivator for transcription factors of the TCF/LEF family, leading to activate Wnt responsive genes. Also acts as a coactivator for other transcription factors, such as NR5A2. Promotes epithelial to mesenchymal transition/mesenchymal to epithelial transition (EMT/MET) via driving transcription of CTNNB1/TCF-target genes. Involved in the regulation of cell adhesion, as component of an E-cadherin:catenin adhesion complex (By similarity). Acts as a negative regulator of centrosome cohesion. Involved in the CDK2/PTPN6/CTNNB1/CEACAM1 pathway of insulin internalization. Blocks anoikis of malignant kidney and intestinal epithelial cells and promotes their anchorage-independent growth by down-regulating DAPK2. Disrupts PML function and PML-NB formation by inhibiting RANBP2-mediated sumoylation of PML. Promotes neurogenesis by maintaining sympathetic neuroblasts within the cell cycle (By similarity). Involved in chondrocyte differentiation via interaction with SOX9: SOX9-binding competes with the binding sites of TCF/LEF within CTNNB1, thereby inhibiting the Wnt signaling (By similarity). Acts as a positive regulator of odontoblast differentiation during mesenchymal tooth germ formation, via promoting the transcription of differentiation factors such as LEF1, BMP2 and BMP4 (By similarity). Activity is repressed in a MSX1-mediated manner at the bell stage of mesenchymal tooth germ formation which prevents premature differentiation of odontoblasts (By similarity).
Synonyms: CTNNB; beta-catenin; armadillo; EVR7; MRD19; NEDSDV
Tractability: Small molecule: a structure with a bound ligand is known; a high-quality ligand is known; it belongs to a druggable protein family. Antibody: UniProt places it where antibodies can reach, with high confidence; its Gene Ontology location is reachable by antibodies, with high confidence; the Human Protein Atlas places it where antibodies can reach. PROTAC: UniProt records ubiquitination sites on it; ubiquitination databases record sites on it; its protein half-life has been measured; a small molecule that binds it is known. Other modalities: a drug acting on it is in phase 2 or 3 trials.
Safety:
Unwanted effects reported when the protein is acted on. In parentheses: how it was acted on, where the effect was seen, and who reports it.
neutropenia (source: ClinPGx)
response to cyclophosphamide, dexamethasone, and thalidomide (source: ClinPGx)
response to thalidomide (source: ClinPGx)
Gene: Protein-coding gene on chromosome 3 (41,194,741 to 41,260,096, forward strand). Ensembl gene ENSG00000168036.
Subcellular location: Cytoplasm; Nucleus; Cytoplasm, cytoskeleton; Cell junction, adherens junction; Cell junction; Cell membrane; Cytoplasm, cytoskeleton, microtubule organizing center, centrosome; Cytoplasm, cytoskeleton, spindle pole; Synapse; Cytoplasm, cytoskeleton, cilium basal body
Subcellular location (Human Protein Atlas): Plasma membrane; Basal body; Cell Junctions; Primary cilium
Pathways (Reactome):
Developmental Biology: Cardiogenesis; Formation of axial mesoderm; Formation of definitive endoderm; Formation of paraxial mesoderm; Formation of the nephric duct; Germ layer formation at gastrulation; Myogenesis; Regulation of MITF-M-dependent genes involved in cell cycle and proliferation; Regulation of MITF-M-dependent genes involved in pigmentation; Somitogenesis; Specification of the neural plate border; Transcriptional and post-translational regulation of MITF-M expression and activity
Signal Transduction: Beta-catenin phosphorylation cascade; Binding of TCF/LEF:CTNNB1 to target gene promoters; Ca2+ pathway; Deactivation of the beta-catenin transactivating complex; Degradation of beta-catenin by the destruction complex; Disassembly of the destruction complex and recruitment of AXIN to the membrane; Formation of the beta-catenin:TCF transactivating complex; RHO GTPases activate IQGAPs; TCF dependent signaling in response to WNT; VEGFR2 mediated vascular permeability
Cell-Cell communication: Activation of STAT3 by cadherin engagement; Adherens junctions interactions; CDH11 homotypic and heterotypic interactions; Degradation of CDH1; Regulation of CDH1 Function; Regulation of CDH1 posttranslational processing and trafficking to plasma membrane; Regulation of CDH11 function; Regulation of CDH19 Expression and Function; SRC activates STAT3 in a quantitative manner, through Cadherin-11 (CDH11), RAC1 and gp130 (IL6ST)
Disease: CTNNB1 S33 mutants aren't phosphorylated; CTNNB1 S37 mutants aren't phosphorylated; CTNNB1 S45 mutants aren't phosphorylated; CTNNB1 T41 mutants aren't phosphorylated; Dengue Virus-Host Interactions; InlA-mediated entry of Listeria monocytogenes into host cells; Signaling by GSK3beta mutants
Gene expression (Transcription): RUNX3 regulates WNT signaling; Transcriptional Regulation by VENTX
and 6 more pathways
Gene Ontology:
Molecular function: alpha-catenin binding; cadherin binding; DNA-binding transcription factor binding; enzyme binding; I-SMAD binding; kinase binding; nuclear estrogen receptor binding; nuclear receptor binding; phosphatase binding; protein binding; RNA polymerase II-specific DNA-binding transcription factor binding; signaling receptor binding; SMAD binding; transcription coactivator activity; transcription corepressor binding; transmembrane transporter binding; ubiquitin protein ligase binding; chromatin binding; histone methyltransferase binding; protein phosphatase binding; transcription coregulator binding; disordered domain specific binding; protein kinase binding
Biological process: adherens junction assembly; canonical Wnt signaling pathway; cell adhesion; cell-cell adhesion mediated by cadherin; cellular response to growth factor stimulus; cellular response to indole-3-methanol; endothelial tube morphogenesis; epidermal growth factor receptor signaling pathway; mesenchymal stem cell differentiation; mesenchymal to epithelial transition; negative regulation of apoptotic process; negative regulation of cell population proliferation; negative regulation of DNA-templated transcription; negative regulation of protein sumoylation; neuron projection extension; osteoblast differentiation; positive regulation of apoptotic process; positive regulation of blood vessel branching; positive regulation of DNA-templated transcription; positive regulation of epithelial to mesenchymal transition; positive regulation of heparan sulfate proteoglycan biosynthetic process; positive regulation of homotypic cell-cell adhesion; positive regulation of neuron apoptotic process; positive regulation of transcription by RNA polymerase II; proteasome-mediated ubiquitin-dependent protein catabolic process; and 54 more
Cellular component: adherens junction; basolateral plasma membrane; beta-catenin destruction complex; beta-catenin-TCF complex; beta-catenin-TCF7L2 complex; catenin complex; cell cortex; cell junction; cell periphery; cell-cell junction; centrosome; cytoplasm; cytosol; euchromatin; extracellular exosome; focal adhesion; lateral plasma membrane; nucleus; perinuclear region of cytoplasm; plasma membrane; protein-containing complex; protein-DNA complex; transcription regulator complex; anchoring junction; chromatin; and 27 more
Genetic constraint (gnomAD): Loss-of-function variants: 6 observed, 85.45 expected, observed/expected ratio (o/e) 0.0702, 90% interval 0.037 to 0.14. The upper end of that interval is the gene's LOEUF score, 0.14, which puts it in group 1 of 6, group 1 being the genes least tolerant of losing a copy. Missense variants: 526 observed, 1,028.5 expected, observed/expected ratio (o/e) 0.51, 90% interval 0.47 to 0.55. Synonymous variants: 312 observed, 350.11 expected, observed/expected ratio (o/e) 0.89, 90% interval 0.81 to 0.98.
Gene-disease validity (ClinGen):
ClinGen rates the evidence that CTNNB1 causes each of these diseases.
CTNNB1-related neurodevelopmental disorder and/or vitreoretinopathy (autosomal dominant): Definitive. Any neurodevelopmental disorder and/or exudative vitreoretinopathy caused by a monoallelic variant in the CTNNB1 gene.
Cancer hallmarks: escaping immune response to cancer (promotes); proliferative signalling (promotes); change of cellular energetics (promotes); escaping programmed cell death (promotes); cell replicative immortality (promotes); genome instability and mutations (suppresses); invasion and metastasis (promotes); angiogenesis (promotes); suppression of growth (promotes); angiogenesis
Homologues: Orthologues: chimpanzee CTNNB1 (100% identical), macaque CTNNB1 (100% identical), guinea pig CTNNB1 (99% identical), mouse Ctnnb1 (99% identical), rat Ctnnb1 (99% identical), pig CTNNB1 (99% identical), dog CTNNB1 (99% identical), rabbit CTNNB1 (95% identical), zebrafish ctnnb2 (95% identical). Paralogues in human: JUP (65% identical), ARMC3 (17% identical), ANKAR (15% identical), ODAD2 (15% identical).
Diseases named in the same sentence as CTNNB1 in open-access papers:
CTNNB1 is named in the same sentence as 537 diseases in open-access papers, as found by Europe PMC text mining. Sharing a sentence is not in itself a finding about the gene and the disease. The quoted sentences say what the papers report.
colorectal cancer (186 papers, 2005 to 2026). A primary or metastatic malignant neoplasm that affects the colon or rectum. "Although Ctnnb1 mutations are uncommon in human colon cancer, Smad4 mutations are associated with poor-prognosis, recurrence and resistance to treatment in colorectal cancer patients and found mutated in 13% of CACs4." (PMID 40386410, 2025). "Several other neoplasms also harbor CTNNB1 point mutations including endometrial, hepatobiliary, and colorectal carcinomas and melanoma." (PMID 39093425, 2025). "Research had indicated that the atypical activation of CTNNB1 was linked to the development of various types of tumors, including but not limited to colorectal cancer, ovarian cancer, prostate cancer, hepatoblastoma, and hepatocellular carcinoma." (PMID 39691708, 2024). "The disease gene association from the CA2 string network for colorectal cancer was found to be prominent with the CTNNB1 (Z-score—7.8) and CDH1 (Z-score—7.2) genes." (PMID 37895185, 2023). "CTNNB1 (catenin beta 1) mutations are involved in development of various cancers, including colorectal cancer, lung cancer, HCC, ovarian and endometrial endometrioid cancer, Wilms tumors, and medulloblastoma." (PMID 36339710, 2022). "The mutations of CTNNB1 gene were seen in pulmonary cancer, breast cancer, colorectal cancer, but also in endometrial and ovarian cancer, including EAOC." (PMID 35012617, 2022). "AOM/DSS-induced murine colorectal cancers frequently carry mutations in Ctnnb1 and Kras and chronic inflammation-related MSI, the Wnt pathway is constitutively activated, closely mirroring human CRC at the molecular level." (PMID 36458816, 2022). "Activating mutations in CTNNB1 have been reported in several cancers, including colorectal cancer, HCC, endometrial cancer, melanoma, ovarian cancer, and thyroid cancer." (PMID 34439356, 2021). "CTNNB1 is altered in 4.81% of colorectal carcinoma patients mutations, which are commonly homo- or hemizygous, indicating a higher threshold of CTNNB1 stabilization to be required for transformation in the colon as compared to extracolonic sites." (PMID 34503164, 2021). "β-catenin activation plays a crucial role for tumourigenesis in the large intestine but except for Lynch syndrome (LS) associated cancers stabilizing mutations of β-catenin gene (CTNNB1) are rare in colorectal cancer (CRC)." (PMID 33115416, 2020). "Hyperactive WNT/CTNNB1 signaling is a hallmark of colorectal cancer, both in early stages of polyp formation and at later stages of invasion and metastasis." (PMID 32083079, 2020). "WNT/CTNNB1 play a central role in the maintenance of multiple adult tissue stem cell populations, and their expression is a hallmark of colorectal cancer in early and later stages." (PMID 33329729, 2020). "Apart from doubling the number of mutated alleles in tumour cells, homozygous CTNNB1 mutations in colorectal cancer also result in a loss of wild type β-catenin, a finding usually associated with inactivation of a tumour suppressor." (PMID 33115416, 2020). "In colorectal cancer cells, missense mutations are frequently found in exon 3 of CTNNB1, which encodes the N-terminal region of β-Catenin, including serine–threonine phosphorylation sites for GSK3β that induce β-Catenin degradation." (PMID 33184430, 2020). "Present study on Pakistani population revealed an association of two non-synonymous polymorphisms in the CTNNB1 gene with colorectal cancer." (PMID 31699039, 2019). "The frequency of mutations in the CTNNB1 gene, which codes for β-catenin, was rare, only two of 200 tumors analyzed were having a mutation in exon 3 at codon 33 and 41 in colorectal cancer tissues." (PMID 31699039, 2019).
colorectal cancer (continued). "In over 90% of all colorectal cancer the β-catenin/WNT signalling pathway is mutated resulting in an accumulation of transcriptionally active CTNNB1 involved in the initiation and progression of this cancer type." (PMID 31544816, 2019). "In this study, the incidence of mutations in the CTNNB1 genes, as well as expression of the CTNNB1 protein in tumor tissue of 200 colorectal cancer subjects, were examined." (PMID 31699039, 2019). "In the present study, we screened a CTNNB1 gene in colorectal cancer samples and investigated the association of CTNNB1 gene mutations in the development of colorectal cancer." (PMID 31699039, 2019). "In summary, the present study on Pakistani population revealed the association of two non-synonymous polymorphisms in the CTNNB1 gene with colorectal cancer." (PMID 31699039, 2019). "APC mutations remain constantly represented in the progression from adenomas to colorectal cancers, while CTNNB1 mutations become less frequent in the tumor spectrum from small adenomas to colorectal cancers." (PMID 29652830, 2018). "Nuclear accumulation and abnormal stabilization of CTNNB1 as a consequence of missense mutations occurs at a high frequency in a variety of epithelial cancers such as colorectal cancer, medulloblastoma, ovarian cancer, and pilomatrixoma." (PMID 28651018, 2017). "Fzd7 can activate Wnt/β-catenin signaling in colorectal cancer cells despite the presence of APC or CTNNB1 mutations." (PMID 29207657, 2017). "For example, in the sensitivity analysis, the CTNNB1 mutation prevalence for colorectal cancer increased from 4.8% to 10.8%, and for lung cancer increased from 2.3% to 8.8%." (PMID 29156750, 2017). "Gain-of-function mutations in the oncogene CTNNB1 (β-catenin encoding gene) are present in approximately 10% of the colorectal cancers." (PMID 26820295, 2016). "Studies in colorectal cancer cell lines have shown that β-catenin (CTNNB1) mutations, and the subsequent aberrant activation of the Wnt signalling pathway, result in upregulation of L1CAM." (PMID 27028855, 2016). "Colorectal cancer is initiated by dysregulation of the canonical WNT signaling cascade whereby mutations in the APC or CTNNB1 gene potentiate tumorigenesis in the colon." (PMID 27070088, 2016). "TNIK regulates Wnt signalling in the most downstream part of the pathway, and its pharmacological inhibition has been expected to block the signal even in colorectal cancer cells with mutation in the APC or CTNNB1 gene." (PMID 27562646, 2016). "Dysregulation of the Wnt pathway leading to accumulation of β-catenin (CTNNB1) is a hallmark of colorectal cancer (CRC)." (PMID 27333864, 2016). "The mutation rate of APC in large intestine cancers is much higher than that of CTNNB1, and the samples harboring APC mutations contained most of those harboring CTNNB1 mutations (78 of 99)." (PMID 26212640, 2015). "Recent sequencing studies with over 200 CRC showed that mutations in β-catenin (CTNNB1) in colorectal cancer are very rare, approximately 5% (11/212)." (PMID 26240067, 2015). "Mutations in the CTNNB1 (β-catenin) gene affect the Wnt pathway and occur in a high percentage of uterine and colorectal cancers, and medullo-blastomas." (PMID 26018524, 2015). "Actually, among 599 genome-wide screened large intestine cancer samples, CTNNB1 (encoding β-catenin protein) was mutated in 99 samples, APC was mutated in 427 samples, and both genes were mutated in 78 samples." (PMID 26212640, 2015). "A key initiation event of colorectal cancers (CRCs) is CTNNB1 stabilization through loss of the APC gene or activating mutations in the CTNNB1 gene." (PMID 24651522, 2014). "This study evaluated the prognostic significance of common genetic variants in the Wnt/APC/CTNNB1 pathway genes on survival in colorectal cancer patients." (PMID 23405266, 2013). "We selected and genotyped 10 tSNP to predict common variants across entire APC and CTNNB1 genes in 282 colorectal cancer patients." (PMID 23405266, 2013).